INS (insulin)
Diseases named in the same sentence as INS in open-access papers (continued):
Sharing a sentence is not in itself a finding about the gene and the disease.
Hypoglycemia (continued). "This ensures all patients on insulin have a standardized hypoglycemia protocol ordered and ready for use." (PMID 35917098, 2022). "Another study was conducted to find out the frequency of the severe hypoglycemia among new users of insulin and oral anti-diabetic drugs." (PMID 36230996, 2022). "Adjusted RRR for hypoglycemia was 13.17 (95% Cl 4.35–39.90) for basal-bolus insulin, 8.92 (95% Cl 2.60–30.63) for premixed insulin, and 2.99 (95% Cl 1.01–8.87) for bolus-only insulin, respectively." (PMID 34986826, 2022). "Most importantly, modern insulin therapy should be focused on physician referral, patient self-monitoring and preventing hypoglycemia with new devices, for example, insulin infusion pumps connected to a continuous glycemia monitor." (PMID 35324747, 2022). "A drop of the circulating blood glucose (e.g., insulin-induced hypoglycemia) is reflected in a way that is dampened and delayed in the brain ISF." (PMID 35619170, 2022). "The physiological role of AAs in stimulating glucagon secretion is most likely to prevent hypoglycemia by increasing AA catabolism and liver gluconeogenesis after protein ingestion, counteracting the anabolic effects of insulin, since AAs also stimulate beta." (PMID 35448534, 2022). "The glucagon stimulation test is an alternative to the insulin-hypoglycemia test for the evaluation of anterior pituitary function in adults and children." (PMID 35723775, 2022). "Hypoglycemia is a fairly common complication in diabetic patients receiving oral or insulin therapy." (PMID 35858952, 2022). "A subcutaneous bolus of insulin (Humulin R) was injected 60 mins before running to replicate the hyperinsulinaemia/hypoglycaemia commonly observed in humans with T1D undertaking exercise." (PMID 36147573, 2022). "A study in United States of America (USA) also indicated that fear of hypoglycemia was one of the most common barriers to insulin treatment." (PMID 35854336, 2022). "Different surveys on patients and physicians found that hypoglycemia related to insulin therapy is the main obstacle that delays insulin initiation and intensification in patients with T2D." (PMID 36554673, 2022). "The compatibility of insulin and glucagon also has to be determined in dual-hormone therapy to minimize the possibility of hypoglycemia." (PMID 36411933, 2022). "The incidence of hypoglycemia was significantly higher in patients initiated with premixed insulin compared with NPH insulin regimens (P < 0.001)." (PMID 36149907, 2022). "In the insulin group, 42% (n = 21) were afraid of hypoglycaemia as compared to only 14% (n = 7) in the OAH group (p = 0.023)." (PMID 35482748, 2022). "The efficiency of insulin release from an INS-loaded HPMC-co-PAM- co-PMAA hydrogel in a simulated rectal microenvironment prompted a subsequent hypoglycemia study." (PMID 35890301, 2022). "Hybrid Closed-Loop (HCL) systems use specific control algorithms which automate basal insulin delivery, based on glucose sensor values for preventing both hypoglycemia and hyperglycemia." (PMID 35351095, 2022). "Subsequent studies have shown that activation of VMHSF1 neurons is required for CRR to insulin-induced hypoglycemia." (PMID 35619170, 2022). "Currently, the effectiveness of combination therapy of insulin with other antihyperglycemic drugs in patients with ACS for the prevention of hypoglycemia is being studied." (PMID 35629267, 2022). "The identification of deaths attributable to hypoglycemia, particularly those resulting from insulin intoxication, is currently a challenge during death investigations." (PMID 36676928, 2022). "Data suggest that up to 58 to 64% of patients treated with insulin and non-insulin therapies require medical assistance for the management of hypoglycemia over a 6-12 month period." (PMID 35164844, 2022). "In situ physiologic intraportal hormone delivery from the pancreatic islets of Langerhans maintains basal normoglycemia with insulin and counterbalances hypoglycemia with glucagon." (PMID 33573247, 2021).
Hypoglycemia (continued). "The body counteracts hypoglycemia by decreasing insulin production while simultaneously increasing glucagon, epinephrine, growth hormone, and cortisol secretion." (PMID 34247627, 2021). "Withdrawal of insulin alone or combination of oral hypoglycemic agents or replacement of insulin formulations or with corticosteroid treatment eliminated hypoglycemia in a few days to 3 months." (PMID 33827670, 2021). "In our previous TREAD-DIAB study, patients under pump therapy had normalized SG levels (with lower rates of hypoglycemia) during sports when using fine-tuning algorithms for insulin dose modifications." (PMID 34512541, 2021). "Stimulation of liver glycogen synthesis is a major direct effect of insulin on the hepatocyte and its elevation results in postprandial hypoglycemia." (PMID 34622807, 2021). "Our sensitivity analysis suggests that the prolonged rise in insulin sensitivity is the driving factor of late-onset hypoglycemia." (PMID 34489869, 2021). "Though the occurrence of hypoglycemia is hard to determine, it is often observed in patients who take insulin regularly." (PMID 33466659, 2021). "About 36.36% of the manuscripts used BG data alone for hypoglycemia prediction; 6.82% of manuscripts predicted hypoglycemia by using BG combined with insulin data, and an equal amount of research work used BG combined with CHO." (PMID 33466659, 2021). "It was previously reported that acute administration of ketones leads to attenuation of the counterregulatory response to insulin-induced hypoglycemia, but studies on the effects of chronic diet-induced ketosis are lacking." (PMID 34444787, 2021). "The most common adverse effects of sulfonylureas are hypoglycemia, mainly because of insulin-induced suppression of hepatic glucose production." (PMID 33467194, 2021). "As insulin secretion suppresses glycogenolysis despite hypoglycemia, ketones levels are normal and ß-hydroxybutyrate is ≤2.7 mmol/L." (PMID 34199977, 2021). "Here we report the levels of soluble neuropilin-1 (sNRP1), NRP1 proteolytic enzyme ADAM9 and NRP1 ligands, VEGF and SEMA3A, in response to insulin-induced hypoglycemia in obese patients with T2D." (PMID 34248841, 2021). "In these rodent studies, GLUT1 upregulation was detected upon insulin injection that induces hypoglycemia." (PMID 34032568, 2021). "Insulin analogues are provided only for patients with type 1 DM or special situations, such as frequent hypoglycemia." (PMID 34118981, 2021). "The change in glucose during exercise was negatively correlated with the pre‐exercise plasma insulin levels, suggesting a role of insulin to induce hypoglycemia during exercise." (PMID 33904659, 2021). "Her mother: “She felt pressured for insulin injections and occasionally felt hypoglycemia in boarding school." (PMID 35002955, 2021). "Although mild hypoglycaemia can be experienced by anyone, severe hypoglycaemia is only a danger for individuals taking certain medications, particularly insulin or sulphonylureas." (PMID 34336909, 2021). "We are aware of only one other study in which C-peptide was infused to determine its effect on insulin-induced hypoglycemia." (PMID 34003799, 2021). "Insulin is a known obesogenic medication, and people often increase their carbohydrate consumption in response to a perceived threat or experience of hypoglycemia." (PMID 34458301, 2021). "We assessed the achievement of FBG < 7 mmol/L on day 7 and the need for sulfonylurea or a long-acting insulin analog (LIA) treatment during hospitalization, which carries a risk of hypoglycemia." (PMID 35050147, 2021). "IDegAsp was more effective than conventional premixed insulin and basal insulin in reducing blood glucose levels with the occurrence of fewer nocturnal hypoglycemia events." (PMID 34564455, 2021).
Hypoglycemia (continued). "Previous studies ascribed the reduced 18F-FDG uptake levels in tumors and inflammatory lesions with insulin-induced hypoglycemia to the effect of insulin, i.e., insulin shifts 18F-FDG from the original area to insulin-sensitive organs." (PMID 34055854, 2021). "The insulin analogs wereadministered twice daily, to avoid a higher requirement in the morning, the need for a big mealin the evening, and hypoglycemia in the afternoon due to physical activity, for 12 weeks." (PMID 35111536, 2021). "Similar to insulin-induced hypoglycemia, 2-DG administration leads to elevated AVP levels in both humans and experimental animals." (PMID 34752420, 2021). "When switching from twice-daily NPH to basal insulin analog, the dosage should be started at 80% of the total NPH dose being discontinued to reduce hypoglycemia risk." (PMID 34165382, 2021). "Notable, bile acids have been suggested to be involved in the pathogenesis of postprandial hypoglycemia via the bile acids-GLP-1-insulin-axis or indirectly via stimulation of FGF-19." (PMID 34084153, 2021). "Fatty acids, found in great quantities in this fruit, also act in the treatment of diseases that affect the nervous system, regulating in a controlled way insulin release, and avoiding hypoglycemia in the brain, mainly in the case of Alzheimer’s disease." (PMID 34681391, 2021). "The mainstay of treatment for T1DM is still insulin therapy, with a varying degree of side effects including hypoglycemia and weight gain." (PMID 33651228, 2021). "One interesting question that remains to be explored is to define the mechanism(s) explaining the few cases of reactive hypoglycaemia reported in the literature given that insulin is commonly expressed in tumours, but hypoglycaemia cases are rare." (PMID 34170845, 2021). "This study investigated the effect of sympathetic denervation of the liver on the iatrogenic insulin‐induced counterregulatory response to hypoglycemia." (PMID 33769710, 2021). "Other studies, in addition, include in situ hybridisation of insulin mRNA, insulin extracted from tumour, cultured cells demonstrating insulin production, granules similar to those in beta cells, and/or cure of hypoglycaemia after tumour extirpation." (PMID 34170845, 2021). "There is still the need to optimize therapy in terms of the potential for hypoglycemia in this patient group and a review of anti-hyperglycemic agents to add on to insulin." (PMID 33402217, 2021). "This has the potential to confuse managing clinicians since normal endogenous C-peptide production by the pancreas is inhibited in response to exogenous insulin-induced hypoglycemia." (PMID 34051096, 2021). "Tissue glucose nadirs in muscle have been reported to be delayed in time and reduced in magnitude relative to glucose in adipose tissue and blood, especially during insulin-induced hypoglycemia." (PMID 33562672, 2021). "Under starvation conditions that lead to hypoglycemia in our experimental setup, however, insulin levels are strongly reduced." (PMID 34032568, 2021). "Inadequate glycogen and reduced fat sources for gluconeogenesis and also high insulin levels in some cases are responsible for hypoglycemia in SGA infants." (PMID 34869090, 2021). "And indeed, induced hypoglycaemia by insulin administration was more commonly performed in these studies." (PMID 33971958, 2021). "For example, when symptoms suggest organic hypoglycemia, the diagnosis of insulinoma will be retained in the case of elevated levels of insulin, pro-insulin and C-peptide after 72 h fasting." (PMID 34885063, 2021). "The serum insulin levels were ≥ 1000 U/mL in 18 patients (40.91%) during the onset of hypoglycemia and 100–1000 U/ml in 42 patients (95.45%)." (PMID 33827670, 2021). "Studies, where pituitary portal blood was sampled, have been able to show that AVP is released preferentially over CRH in some cases, including insulin-induced hypoglycemia." (PMID 33905792, 2021).
Hypoglycemia (continued). "Insulin had significantly higher prematurity, small for gestational age, and hypoglycemia [OR=1.89, 2.53, and 2.84, respectively]." (PMID 34290797, 2021). "Previous studies in KD-fed nondiabetic mice reported an impairment in glucagon secretion in response to insulin-induced hypoglycemia." (PMID 34444787, 2021). "In response to insulin-induced hypoglycemia, arterial lactate concentrations increased slightly, but similarly, in both treatments, as did net hepatic lactate uptake." (PMID 34003799, 2021). "Compared to the wild-type, our RIN-m(-/-Adcy7) demonstrated an increase in the acute insulin activity leading to a 54% higher secretion during hypoglycemia in vitro." (PMID 34177802, 2021). "When compared to optimal insulin therapy, IT demonstrated higher efficacy in reducing severe hypoglycemia and preventing microvascular complications." (PMID 33755854, 2021). "Here, we showed that insulin‐induced hypoglycaemia triggers a robust feeding response in STZ‐diabetic rats and treatment with 2DG significantly reduced the feeding response, suggesting the animals have impaired awareness of hypoglycaemia." (PMID 33855225, 2021). "Patients with nocturnal hypoglycaemia were mostly on insulin treatment (1854 (78.5%) patients with 20,727 (84.1%) hypoglycaemic glucose values)." (PMID 33672913, 2021). "As such, an adjunct agent for insulin to provide decreasing hypoglycemia, weight gain, blood pressure, and GV is necessarily needed." (PMID 34497852, 2021). "We suggest that future studies of dantrolene or similar agents track changes in total daily insulin dose (with percentage basal versus bolus) and analyze continuous glucose monitor tracings (i.e., time in range, time in hypoglycemia, and standard deviation)." (PMID 34185708, 2021). "The present study showed that insulin-mediated TO-induced hypoglycaemia resulted in the stimulation of glycolysis and pyruvate production via insulin-dependent and insulin-independent mechanisms." (PMID 33997754, 2021). "Before initiating insulin therapy, the physician should ensure the patient will be able to monitor blood glucose levels, is aware of hypoglycaemia symptoms, and knows how to deal with hypoglycaemic episodes." (PMID 33098260, 2021). "However, the risk of severe hypoglycemia in a neonate may outweigh the benefits of insulin." (PMID 33879184, 2021). "The DCCT also demonstrated that achieving tighter glycemic targets in adolescents and adults is limited by insulin-induced hypoglycemia." (PMID 37745178, 2021). "In this study, we show that NCD-fed Rptorob−/− mice displayed a marked metabolic phenotype characterized by low fat mass, hypoglycemia, enhanced glucose tolerance, and increased insulin sensitivity." (PMID 33551450, 2021). "In 15% of cases, a functional syndrome (FS) (hypoglycemia, recurrent gastric ulcers, necrolytic migrating erythema) is present, which is related to hormone production (e.g. insulin, gastrin, glucagon)." (PMID 34025587, 2021). "Another CGM study demonstrated that males were more likely to develop hypoglycemia than females in T2DM patients on insulin therapy." (PMID 33649395, 2021). "The decrease in blood glucose levels below the normal i.e., hypoglycemia, is the major side effect of insulin and oral hypoglycemic agents." (PMID 34040519, 2021). "The most relevant limiting factor for achieving good glycemic levels is hypoglycemia, defined as glycemic values lower than 70 mg/dl (3.9 mmol/L), determined by a discrepancy between insulin administration and carbohydrate (CHO) intake." (PMID 33755854, 2021). "LGS systems suspend insulin delivery when the CGM-reported BG hits a pre-set hypoglycemia threshold." (PMID 37745178, 2021). "A relative maternal hypoglycemia would lead to acute or chronic decrease in fetal glucose and insulin and, considering that insulin is a hormone involved in fetal growth, would hypothetically predispose to intrauterine growth restriction (IUGR) and LBW." (PMID 34008784, 2021).
Hypoglycemia (continued). "In terms of treatment, in the current study, patients who had received a high frequency of counseling about insulin pen since their diagnosis were more likely to have good knowledge about hypoglycemia and insulin use." (PMID 34497858, 2021). "The requirement for a lower glucose infusion rate in GhIRKO mice and their higher plasma GH levels during hyperinsulinemic-hypoglycemic clamps emphasize ghrelin’s key involvement in the counterregulatory response to insulin-induced hypoglycemia." (PMID 34473648, 2021). "Compared to the CON group, high mortality, growth retardation, fasting hypoglycemia, reduced plasma insulin, and oxidative stress were observed in the PAD group." (PMID 34193047, 2021). "The severity and duration of hypoglycemia and the swing from a hyperglycemic to a hypoglycemic state are closely related to the binding characteristics of insulin to IAA i.e. intrinsic dissociation rate constant (K-1), titer and intrinsic affinity/capacity." (PMID 33827670, 2021). "Experimental studies on the other hand while more controlled require supra-physiological concentrations of insulin to induce hypoglycaemia, rarely encountered in clinical practice." (PMID 34814734, 2021). "Insulin-induced hypoglycemia provoked a more dramatic increase in the levels of CD31+ and CD105+ endothelial microparticles in individuals with T2D compared to controls." (PMID 34360550, 2021). "It has been reported that insulin-induced hypoglycemia leads to an upregulation of GLUT1 mRNA as well as protein in rat BBB-forming endothelial cells." (PMID 34032568, 2021). "Although many people with T2D have difficulty achieving glucose targets and therefore meet criteria for insulin therapy, a major barrier to treatment intensification is the fear of hypoglycaemia." (PMID 33950566, 2021). "Patients with schizophrenia reported a reduction in or the disappearance of all sorts of hallucinations during insulin-induced hypoglycemia and a protraction of the lucid phase’, thus proving the clinical evidence of a psychotropic effect of insulin." (PMID 33799976, 2021). "Due to the anabolic insulin effect, low/undetectable levels of ketones and fatty acids are characteristically recorded during hypoglycemia." (PMID 34635134, 2021). "Three studies demonstrated the similarity of this glucagon molecule and of traditional glucagon kits in insulin-induced hypoglycemia in adults and children." (PMID 34638984, 2021). "Regarding safety, we investigated the event rates of overall hypoglycemia and nocturnal hypoglycemia with IDegAsp and other insulin therapies." (PMID 34564455, 2021). "When compared to insulin glargine, degludec has comparable efficacy but demonstrates less nocturnal hypoglycemia in adults." (PMID 37745178, 2021). "We established insulin-induced hypoglycemia in mice, a commonly used acute physical stress model, to investigate the expression of mimecan after acute stress." (PMID 33971622, 2021). "Adverse reactions to insulin (e.g. hypoglycemia or weight gain) and financial difficulties played a smaller role than blood glucose control (in an area with a high penetration of health insurance)." (PMID 33402226, 2021). "Other potentially atherogenic adverse effects of high doses of insulin in T2D include weight gain, recurrent hypoglycemia, and iatrogenic hyperinsulinemia." (PMID 35011813, 2021). "Hyperinsulinemic hypoglycemia with high C-peptide usually indicates endogenous insulin hypersecretion." (PMID 34051096, 2021). "AVP also mediates the stimulatory effects of hypoglycemia produced by exogenous insulin and 2-deoxy-D-glucose on glucagon secretion." (PMID 34787082, 2021). "Another sulfonylurea-receptor-binding drug, sulfonylureas, affects pancreatic β cells, leading to augmented insulin secretion and possibly hypoglycemia." (PMID 34203830, 2021). "Subcutaneous administration of insulin can result in periods of hypoglycemia post-administration, but this effect can be alleviated by oral carbohydrates given in parallel." (PMID 34947937, 2021).